CD34 (CD34 molecule)
Diseases named in the same sentence as CD34 in open-access papers (continued):
Sharing a sentence is not in itself a finding about the gene and the disease.
tumor (continued). "Regarding CD34 expression, overall mean number of positive cells was 64% (SD: 35.6%): mean rates of 86%, 90% and 19% positive cells were observed in grade I, II and III tumours, respectively (p<0.001)." (PMID 30183767, 2018). "Analysis of serial tumor biopsies prior to and following 2 weeks of ENMD-2076 (n = 8 patients) demonstrated a treatment-induced decrease in cellular proliferation (Ki-67) and MVD (CD34) as assessed by IHC." (PMID 30071865, 2018). "Promoter activity levels were measured in normal hematopoietic cells (progenitor hematopoietic cells (CD34+) and B-cells (CD19+) and T-cells (CD3+) of peripheral blood) and tumor cell lines (Namalwa and Raji B-cell lymphoblastomas and Jurkat T-cell lymphoblastoma)." (PMID 30042821, 2018). "Tumour grade along with immunohistochemistry for Ki67, STAT6, PHH3, CD34 and Bcl-2 were assessed." (PMID 30183767, 2018). "Taking into consideration the following characteristics: age, sex, histopathological grading, tumor size (T feature), clinical staging (TNM), MVD/CD34, and MVD/CD105, we built a multivariate logistic regression model containing characteristics considered significant for patient survival." (PMID 29748768, 2018). "It is generally thought that endoglin (CD105) rather than CD34 is expressed in the vascular endothelium of tumor vessels forming de novo." (PMID 29748768, 2018). "In this murine model, CD34− and Sox2− cells were both able to form tumours after transplantation, producing CD34- and Sox2-positive and -negative populations in similar proportions to the parental tumour." (PMID 29991569, 2018). "The tumor mass was detected in the left lung of a 75-year-old man and showed positive immunostaining for cytokeratin (CK) 7, CK8, smooth muscle actin, CD31, and CD34." (PMID 30263099, 2018). "The therapeutic potential and activity of LY3300054 in the context of more completely human immune-replete animals was assessed in immunodeficient NSG or NOG mice engrafted with HSCs of human origin (CD34+ huHSCs), and two xenograft mouse tumor models, using the HCC827 and OV79 tumor cell lines." (PMID 29712568, 2018). "Remarkably, in the tumor area, a neo-vascular formation with a “mosaic” structure was observed with a double staining of CD34 and NHERF1, which could indicate a probable tumor cell recruitment in neo blood vessels formation with endothelial cells." (PMID 29716631, 2018). "To address this, we have innovated a platform to reconstitute autologous HIS in immunodeficient NOG-EXL mice with mobilized peripheral blood (MPB)-CD34 cells derived from a head and neck cancer patients along with PDX generated from the same patient tumor tissue." (PMID 30400822, 2018). "Immunohistochemically, the tumor cells expressed STAT6 and CD34." (PMID 30168002, 2018). "We show that these cells infiltrate and possibly predispose the local microenvironment for the successful settling of disseminated NRAS‐mutant tumor cells, and include CD45+CD11b+Ly6c+ and CD45+CD11b+Ly6g+ hematopoietic as well as CXCR2+CD34+ endothelial progenitors." (PMID 28341702, 2017). "The immunohistochemical profile, including c-kit and CD34 co-expression and absence of desmin and actin, specifically identified this tumor as GIST outside the tubular gastrointestinal tract." (PMID 28421549, 2017). "CD20 and CD34 staining revealed that the tumor cells were not involved in the right lobe of the thyroid or the central neck area lymph nodes." (PMID 28841887, 2017). "The tumor tissue in 2005 was a round white-tan mass with characteristic DFSP phenotypic features, such as storiform and infiltrative growth pattern and positive immunohistochemical (IHC) staining for CD34." (PMID 28977029, 2017). "Core needle biopsy of the tumor revealed bundles of spindle cells with positive immunohistochemical staining for c-kit and CD34, but negative for S100 proteins." (PMID 28058590, 2017).
tumor (continued). "By immunohistochemistry, some tumor cells were weakly positive for epithelial membrane antigen (EMA), but they were negative for cytokeratin, smooth muscle actin (SMA), desmin, S-100, Melan-A, and CD34." (PMID 28471957, 2017). "Three-dimensional cultures may promote the expression of CD34, VEGF-A, PDGF-B, and bFGF better than 2D cultures in xenograft tumours in vivo." (PMID 28515673, 2017). "The observed CD34+ and VEGFR2+ tumor vascular counts in individual cases were heterogeneous." (PMID 28533703, 2017). "Immunohistochemical (IHC) staining of the patient’s tumour revealed only focal SMA positivity, whereas the tumour was negative for Desmin, Caldesmon, S100, CD34, EMA, Melan A, and Pan-CK." (PMID 28304377, 2017). "Tumours treated with either nsPEFs alone or everolimus alone exhibited decreased VEGF, VEGFR, and CD34 expression, while the combined treatment showed an increased inhibition of VEGF, VEGFR, and CD34 expression, indicating that nsPEFs and everolimus synergistically suppressed neovascular growth." (PMID 28054548, 2017). "Histologic and immunohistochemical criteria of sarcomatous changes are cellular atypia, a fascicular pattern, ten mitoses per 10 high-power fields at × 40 magnification, decreased expression of CD34, and increased MIB-1 (EB1) with more than 5% of tumor tissue transformed." (PMID 28388964, 2017). "We confirmed that the GEF ELMO1 is co-expressed with CD34-positive tumor epithelial cells at the protein level by immunofluorescence staining and observed increased staining of this RAC-activating factor at the leading edge of the tumor." (PMID 28219480, 2017). "Finally, comparison of CD34+ and CD4+CD8+ healthy donor thymocytes and T-ALL miRNA profiles allowed identifying several novel miRNAs with putative oncogenic or tumor suppressor functions in T-ALL." (PMID 28801656, 2017). "Similar kinetics of CD34+ circles and infiltrating T cells were observed when these parameters were compared before and after tumor recurrence/progression; compared to recurrent GBM, significantly increased CD34+ circles and T cell subsets were found in secondary GBM." (PMID 29163521, 2017). "The chRNAs were classified by their relative expression in normal CD34+ HSCs, in order to distinguish non-tumor and tumor-specific ones." (PMID 29623188, 2017). "On immunohistochemistry, the tumor was positive for CD34 and CD99 and negative for α-SMA, S-100, and bcl-2." (PMID 28326216, 2017). "Serial transplantation of Itgav+ tumor cells failed to generate CD34+ or Lgr6+ cancer cells as shown by flow cytometry." (PMID 29113290, 2017). "DP tumor cells express CD34 but not PS100 and factor VIIIa, in contrast to diffuse neurofibroma, which expresses PS100." (PMID 28388964, 2017). "On immunohistochemistry tumor cells exhibit strong diffuse positivity with smooth muscle actin and vimentin, and are negative for cytokeratin, CD34 and S100." (PMID 29216875, 2017). "Mean CD34+ and VEGFR2+ tumor vessel counts were 11 and 3.4 per tumor TMA core respectively." (PMID 28533703, 2017). "Histological evaluation of the septated, cystic mass revealed tumour cells forming an irregular patternless pattern; immunohistochemically, the cells tested positive for vimentin, CD34, CD99 and STAT6 but negative for keratin (AE1-AE3), CD31 and S100." (PMID 28865431, 2017). "On immunohistochemical examination, the tumor cells were negative for desmin, S100, smooth muscle actin, CD34, and CD117 and were positive for MUC4." (PMID 27247823, 2016).
tumor (continued). "IHC analysis revealed that both the control tumor and celecoxib-treated tumor harbored CD34-positive vascular channels and CD34-negative VM structures." (PMID 27824617, 2016). "Diffuse positive staining of tumor cells with CD31, CD34, and D2-40 favored their vascular origin." (PMID 27747121, 2016). "To assess whether the reduced tumor size/weight in Oct4A KD cell-derived tumors may result from reduced tumor vascularity, we assessed the expression of human specific angiogenesis markers CD31 and CD34 on mouse xenografts." (PMID 27390927, 2016). "Moreover, as with CD34 mRNA-electroporated NK cells, NK cells electroporated with CCR7 mRNA maintained potent cytotoxicity function against tumor cells." (PMID 27047492, 2016). "An anti‐CD68 antibody was employed to assess TAMs and TAMIA expression, an anti‐CD34 antibody was utilized to detect MVD and EA expression, whereas an anti‐VEGF‐A antibody was used to detect CCP‐VEGF‐A; then, tumour sections were evaluated by image analysis methods." (PMID 27105577, 2016). "Since VM has no endothelial cells and is consisted of tumor cells with basement membrane components, it is not stained by CD34 but stained positively by PAS." (PMID 27793002, 2016). "In normal liver and in histologically normal liver which was 1.5 cm distant from tumor, there was no expression of CD34-positive microvessels." (PMID 26934653, 2016). "Tumor cells in the elevated and atrophic plaques stained positive for CD34 and vimentin and stained negative for factor XIIIa and α-smooth muscle actin." (PMID 26932148, 2016). "A role of CD34 in tumor angiogenesis was suggested by the observation that Cd34 deletion in mice (specifically in non-hematopoietic lineages) impaired early tumor growth due to a delay in angiogenesis." (PMID 27352134, 2016). "In addition, the sensitizing effect of GCS inhibition by PDMP was accompanied by reduced tumor cell proliferation, as denoted by PCNA detection and vascularization, as detected in CD34 stained slides." (PMID 26811497, 2016). "The CD3CAR NK-92 cells lysed over 50% of CD3+ T-cells at an E:T ratio of 5:1, with no change observed in the CD34+ CD3- tumor population." (PMID 27494836, 2016). "In support of cell-based findings, we also found a significant negative correlation between intratumoral IL-37 expression and tumor angiogenesis measured as CD34-determined intratumoral MVD in human NSCLC samples, suggesting an inhibitory role of IL-37 in the tumor angiogenesis." (PMID 26791086, 2016). "Immunohistochemically, tumor cells were positive for CD34 and HHF-35, but negative for cytokeratin, HMB-45 and Melan-A." (PMID 26754205, 2016). "In contrast to CD34/K15+ quiescent bulge stem cells, actively proliferating Lgr5+ stem cells do therefore not appear to be tumor drivers in experimental skin carcinogenesis." (PMID 27409834, 2016). "On the other hand, the depletion of PLCγ1 by shRNA3 led to the decrease in CD34 (one of biomarkers of vascular density) and VEGF protein levels, and VEGF mRNA level in tumor tissue, indicating the involvement of PLCγ1 in the angiogenesis of tumor (*P < 0.05, ****P < 0.0001, vs control)." (PMID 26811493, 2016). "The immunohistochemical study showed strong and diffuse immune response for S100 protein in tumor cells and negative response for CD34 or smooth muscle actin (SMA)." (PMID 27882056, 2016). "The LV-miR-497 group displayed reduced AEG-1, CD34 and VEGFA expression in the tumor tissues." (PMID 26336827, 2015). "The tumor cells expressed CD34, bcl-2, CD99, and vimentin and were negative for LCA (leukocyte common antigen), desmin, SMA (smooth muscle antigen), CK7, CK34, BE12, CK19, and CK20." (PMID 25688313, 2015). "Immunohistochemical staining showed that vimentin and SMA were positively expressed in these tumor cells, while desmin was only partially expressed; in contrast, no sign of S-100 or CD34 protein expression was found in these spindle-shaped tumor cells." (PMID 26303928, 2015).
tumor (continued). "His immunohistochemistry analysis showed that the tumor cells were positive for vimentin, CD34, BCL-2 and beta-catenin, and negative for pan Cytokeratin, p63, Calretinin, SMA, desmin, S100, CD-31, CD-117, DOG1, EMA, STAT6, GRIA2 and WT-1." (PMID 25884588, 2015). "High densities of macrophages and endothelial cells (CD34), prominent in SLN+, infiltrate SLN and may reflect a tumor favorable microenvironment." (PMID 26218530, 2015). "Tumor invasion and high density of CD68+ and CD34+ cells increased in SLN+ may reflect a tumor favorable microenvironment." (PMID 26218530, 2015). "Moreover, OCT4B enhanced angiogenesis by the upregulation of CD34, VEGF, HIF-1α and IL-6, and promoted tumor cell mobility to the surrounding tissue by the upregulation of MMP2 and MMP9, and the induction of epithelial-mesenchymal transition (EMT)." (PMID 25816351, 2015). "Staining for CD34, synaptophysin, and chromogranin A revealed that they were not expressed in these tumor cells." (PMID 26697255, 2015). "Second, by mice tumor tissues, we used IHC to determine a negative association of the expression of VEGF, CD31, and CD34 as well as MVD status with CDK11 expression." (PMID 26470709, 2015). "In the present case, the tumour cells were strongly positive for CD34 and Bcl-2, but were negative for CD117, smooth muscle antigen, S-100, EMA and desmin expression, indicating that the tumour was an SFT." (PMID 25663869, 2015). "Significant higher level of CD34 was detected in the tumor tissue than the adjacent nontumorous tissue." (PMID 26336827, 2015). "Immunohistochemically, the tumor cells of the overwhelming majority cases stain for S-100 protein, while CD34 staining is negative." (PMID 25621027, 2015). "In contrast, both intermediate (Group 2) and mature (Group 3) blastic pDC neoplasms showed no blast/tumor cell population other than the pDC, all these cases being systematically negative for CD34 by definition." (PMID 26056082, 2015). "Immunohistochemical staining showed strong expression of vimentin and smooth muscle actin (SMA) in the tumor cells, while desmin was only partially expressed; however, no sign of S-100 protein or CD34 expression was found in these cells." (PMID 26303928, 2015). "The tumor miR146a expression was negatively correlated with the density of activated microglial cells (r = −0.400, p = 0.043) and CD34 expression (r = −0.541, p = 0.037; not endothelial cells)." (PMID 25986346, 2015). "This expression was significantly related to CD34-positive vessels, but not to the tumor invasion grade or age, sex, or tumor size." (PMID 25834571, 2015). "Immunohistochemical studies in three cases demonstrated that the tumor cells were positive for CD34, vimentin, SMA, and HMB-45, but negative for S-100." (PMID 26391670, 2015). "Tumor cells expressed smooth-muscle-actin, CD31, CD34, and progesterone receptor." (PMID 26351605, 2015). "Insignificant differences were noticed between the percentages of area occupied by CD34+ endothelial cells/mm2 at the tumor periphery and in the normal breast tissue." (PMID 25652007, 2015). "In LNCaP tumor tissues, CD31 and CD34 were declined by 50% and 49.09% respectively in combination treatment group compared with vehicle control (P<0.01), and at the same time, quercetin or 2-ME alone also brought about downregulation of CD31 and CD34 (Quercetin: 27.45% for CD31, 30% for CD34." (PMID 26011145, 2015). "The tumor cells from the two maxillary LGMSs, including the recurrent lesion, were positive for vimentin and fibronectin, and negative for S-100 protein, CD34, EMA, h-caldesmon, ALK, MSA and calponin." (PMID 25624890, 2015). "Our results show that blasts from cases with an immature plasmacytoid dendritic cell (pDC) phenotype exhibit an uncommon CD56− phenotype, coexisting with CD34+ non-pDC tumor cells, typically in the absence of extramedullary (e.g. skin) disease at presentation." (PMID 26056082, 2015).
tumor (continued). "Tumour cells are consistently negative for S-100protein (40/40 cases, 100 %), while they show positivity for CD34 in 45.4 % (20/44) of the cases." (PMID 26187500, 2015). "Other factors, including primary site, metastasis at diagnosis, radiation use, concurrent second malignancy, tumor size, CD34 status and mitotic count, were not been found to be significantly associated with overall survival." (PMID 26469269, 2015). "Immunohistochemical staining revealed that the tumor cells were differentiated into fibroblastic and myofibroblastic, which are strongly positive for vimentin and SMA, and weakly positive for desmin and CD34." (PMID 26303928, 2015). "All tumor cells stained positive for CD34 but were negative for desmin, CD31, S100, HMB-45, synaptophysin, chromogranin, and WT-1." (PMID 25177679, 2014). "The reason for the negative c-kit and positive CD34 findings, despite the tumor being positive for both markers preoperatively, is unclear." (PMID 24575748, 2014). "In our case, tumor cells were positive for CD34 and CD31 and negative for AE1/3, CK8/18, CD10, and RCC." (PMID 25133004, 2014). "Tumor angiogenesis can be quantified by microvascular density (MVD), which is evaluated in highly vascularized tumor areas (hot spots) by immunohistochemical assays using CD34 and CD31 pan-endothelial antibodies." (PMID 24507660, 2014). "Staining for AE1/AE3, S-100, smooth muscle actin (SMA), desmin, cluster of differentiation 31 (CD31), CD34 and anaplastic lymphoma receptor tyrosine kinase (ALK) was negative, while the staining for vimentin was strongly positive (+++) with >50% positive tumor cells." (PMID 24959221, 2014). "As TGFβ is well known to regulate tumor growth and metastasis, and supports the maintenance of stem cells, we hypothesized that TAM-derived TGFβ might be involved in promoting CD34− TIC survival." (PMID 25294815, 2014). "Immunohistological studies revealed that the tumor yielded positive staining for p63, vimentin, CD34 and CD68, but was negative for SMA, CD38 and cytokeratin." (PMID 25120721, 2014). "Immunohistochemically, these neoplastic cells stained positively for epithelial membrane antigen (EMA), but the tumor cells failed to stain for S100 protein, CD34 or smooth muscle actin (SMA)." (PMID 24410763, 2014). "Immunohistochemical staining demonstrated that the tumor cells were diffusely positive for CD34 and Mic-2 whereas staining for actin and EMA was negative." (PMID 25197592, 2014). "The tumor volume and the immunohistochemical analysis of CD31, CD34 and VEGF were determined." (PMID 24901647, 2014). "The tumor cells were negative for cluster of differentiation 34 (CD34), B cell lymphoma/lewkmia-2 and anaplastic lymphoma kinase, which eliminated the possibility of a solitary fibrous tumor or inflammatory myofibroblastic tumor." (PMID 24444015, 2014). "The level of VEGF-A expression did not correlate with vascularization in tumours: the analysis of tumours using the blood-vessel marker CD34 showed a similar vascular pattern in SC+ORT and ORT groups in primary tumours of both HCT116 and SW48 xenografts." (PMID 24487410, 2014). "The tumor staining gave a negative result with CD34, actin, and EMA and a positive result with MIC-2 and the tumor showed high mitotic activity." (PMID 25197592, 2014). "To measure vasculature in the tumor samples, we measured microvessel area (MVA) by CD-34 staining." (PMID 24423208, 2014). "Immunohistochemical study showed that the tumor cells were strongly positive to vimentin, α-smooth muscle actin, and muscle specific actin and negative to CD34." (PMID 25143851, 2014). "Immunohistochemistry showed that these tumor cells were positive for desmin, smooth muscle actin, estrogen receptor, and progesterone receptor and negative for S100, CD117, and CD34, confirming the smooth muscle origin of the tumor." (PMID 24991446, 2014). "Immunohistologically, the tumor cells stained positive for smooth muscle actin and negative for S-100, CD34 and actin." (PMID 24396463, 2014).